TRAV36DV7 (T cell receptor alpha variable 36/delta variable 7)
Description:
V region of the variable domain of T cell receptor (TR) alpha chain that participates in the antigen recognition. Alpha-beta T cell receptors are antigen specific receptors which are essential to the immune response and are present on the cell surface of T lymphocytes. Recognize peptide-major histocompatibility (MH) (pMH) complexes that are displayed by antigen presenting cells (APC), a prerequisite for efficient T cell adaptive immunity against pathogens. Binding of alpha-beta TR to pMH complex initiates TR-CD3 clustering on the cell surface and intracellular activation of LCK that phosphorylates the ITAM motifs of CD3G, CD3D, CD3E and CD247 enabling the recruitment of ZAP70. In turn ZAP70 phosphorylates LAT, which recruits numerous signaling molecules to form the LAT signalosome. The LAT signalosome propagates signal branching to three major signaling pathways, the calcium, the mitogen-activated protein kinase (MAPK) kinase and the nuclear factor NF-kappa-B (NF-kB) pathways, leading to the mobilization of transcription factors that are critical for gene expression and essential for T cell growth and differentiation. The T cell repertoire is generated in the thymus, by V-(D)-J rearrangement. This repertoire is then shaped by intrathymic selection events to generate a peripheral T cell pool of self-MH restricted, non-autoaggressive T cells. Post-thymic interaction of alpha-beta TR with the pMH complexes shapes TR structural and functional avidity.
Synonyms: TRAV36/DV7; TCRAV28S1; hADV36S1
Gene: T-cell receptor variable (V) gene on chromosome 14 (22,226,746 to 22,227,254, forward strand). Ensembl gene ENSG00000211815.
Subcellular location: Cell membrane
Gene Ontology:
Biological process: response to bacterium
Cellular component: plasma membrane
Homologues: Orthologues: macaque TRAV36DV7 (91% identical). Paralogues in human: TRAV20 (49% identical), TRAV24 (47% identical), TRAV21 (45% identical), TRAV39 (42% identical), TRAV10 (41% identical), TRAV7 (41% identical), TRAV5 (38% identical), TRAV13-1 (36% identical), TRAV27 (35% identical), TRAV34 (35% identical), TRAV13-2 (35% identical), TRAV17 (35% identical), and 11 more.